POU2F3 (POU class 2 homeobox 3)
Diseases named in the same sentence as POU2F3 in open-access papers (continued):
Sharing a sentence is not in itself a finding about the gene and the disease.
cancer (25 papers, 2016 to 2025). A tumor composed of atypical neoplastic, often pleomorphic cells that invade other tissues. "Recent studies have revealed their significant role in cancer biology, particularly through the expression of the transcription factor POU2F3, which serves as a master regulator of tuft cell lineage." (PMID 42211052, 2025). "In this review, we first analyze the expression patterns of POU2F3 across cancer types using the TCGA datasets, revealing differential expression profiles and supporting the classification of tuft cell-like subtypes." (PMID 42211052, 2025). "Using this assay, we also detected the known interaction between RUVBL1/2 and MYC47, as well as interactions with other cancer-promoting TFs, including POU2F3 and MYB." (PMID 41241675, 2025). "Tumors expressing POU2F3 are considered tuft-cell-like carcinomas and exhibit a range of histologic types beyond HGNEC." (PMID 40406790, 2025). "The frequencies of POU2F3 expression also differed among subtypes and were significantly higher in benign than malignant tumors (22/28 vs. 9/25, P = 0.001)." (PMID 38358561, 2024). "We also detected POU2F3 immunoreactivity in mucoepidermoid (1/2) and lymphoepithelial (2/2) carcinomas of the thymus, which to our knowledge is the first immunohistochemical detection of POU2F3 in these carcinoma subtypes." (PMID 37190202, 2023). "Some of them are cancer related, such as POU2F3, NKD1 and CYP2C8, while LINC00189, GCC2 and OR9Q1 genes are rarely reported in human diseases." (PMID 27602771, 2016). "Understanding the tuft cell-like-POU2F3 axis could open new avenues for targeted therapies in lineage-defined cancers." (PMID 42211052, 2025). "To this end, using a recently marketed anti-POU2F3 antibody, unavailable when we performed IHC analyses for cancer TMA tissues, might be helpful." (PMID 37179317, 2023). "Although data are lacking to support a direct interaction between POU2F3 and SOX9 in normal tuft cells, a recent SCLC (i.e., cancer) study reported the direct binding of POU2F3 (and its cofactor, POU2AF2) to the SOX9 gene locus in tuft cell-like SCLC cell lines." (PMID 37179317, 2023). "In summary, we have summarized the role of tuft cells in tumors and indicated the potential possibilities of tuft cells as a novel target for tumor treatment, and strategies targeting specific molecules including DCLK1 and POU2F3 can become good choices for cancers with tuft cell signatures." (PMID 36569325, 2022). "All hub genes except POU2F3 showed significant differential expression in different cancer types." (PMID 34301206, 2021). "We conducted a coexpression analysis of PGC-1α against the four SCNC lineage markers—ASCL1, POU2F3, NEUROD1, and YAP1—across all 1,466 human cancer cell lines from the Cancer Cell Line Encyclopedia (CCLE)." (PMID 39589879, 2024). "Because KIT and BCL2 are often highly expressed in POU2F3-positive tuft cell-like carcinomas, the same feature in WTs could suggest that non-neoplastic POU2F3-positive cells might express BCL2 and KIT via non-mutational, possibly epigenetic mechanisms that, in turn, might be smoking-related." (PMID 38358561, 2024). "Two of the four cancers contained both invasive and DCIS components, and the latter also expressed POU2F3." (PMID 37179317, 2023). "First, we downloaded the bulk expression data for 50 SCLC cell lines from the Cancer Cell Line Encyclopedia (CCLE) and categorized them according to the key TFs ASCL1, NEUROD1, POU2F3 and YAP1." (PMID 36195615, 2022). "In addition to subtype markers (ASCL1, NEUROD1, POU2F3, and YAP1), the expression of nine cancer-specific proteins was evaluated." (PMID 40107154, 2025). "constructs a novel model of SCLC subtypes defined by differential expression of four key transcription regulators: ASCL1, NeuroD1, YAP1, and POU2F3 according to SCLC primary human tumors, patient-derived xenografts, cancer cell lines, and genetically engineered mouse models." (PMID 40433367, 2025).
cancer (continued). "For example, both POU2F3 and SOX10 also bind RUVBL1/2 in an ATPase-dependent manner, and RUVBL1/2 inhibition broadly suppresses lineage-specific gene expression across several cancer types." (PMID 41241675, 2025). "Notably, accumulating evidence has shown that the specific genes (POU2F3, DCLK1) expressed in tuft cells are involved in vital processes related with carcinogenesis and cancer development." (PMID 36569325, 2022). "On the other hand, “hub genes” of four other modules contain POU2F3 (↑), CENPH (↑), PCSK6 (↑) and HERC2 (↑), BCAR3 (↑), DOHH (↑), NLK (↑), SCN2A (↑), CACNA2D3 (↓) and CTNND2 (↓), which were commonly reported related to cancer." (PMID 27602771, 2016). "More recently, in tuft cell-like SCLC cells, the coactivators of POU2F3 (POU2AF2 and POU2AF3) were found to endow POU2F3 with a critical transactivation domain by forming a master regulator complex, which supports enhancer-mediated cancer-promoting gene activation in SCLC-P cells." (PMID 38328238, 2024). "In WTs, POU2F3-positive cells tended to be on the abluminal side when two layers were recognizable and, at least partly, co-expressed p63 and p40, common abluminal markers, along with KIT and BCL2, which are often expressed in carcinomas with tuft cell-like phenotype." (PMID 38358561, 2024). "Of note, a recent study on the transcriptional mechanism of the tuft cell lineage identified a critical transcriptional complex composed of POU2F3, OCA-T1, and OCA-T2; these interactions may become an important target for pharmacological blockade in tuft cell-like carcinomas." (PMID 38168015, 2024).
infection (21 papers, 2011 to 2025). The state of being infected such as from the introduction of a foreign agent such as serum, vaccine, antigenic substance or organism. "Animals of the resistant breed had significantly greater numbers of POU2F3+ cells and Th2 cells in the abomasal epithelium compared to susceptible animals following infection and a strong correlation between ovine POU2F3+ cells, Th2 frequency and nematode clearance was identified." (PMID 34880874, 2021). "Thus, local enteric events and systemic immunity in Pou2f3-/- mice were examined for deficiencies that could account for the prolonged infection with H. diminuta." (PMID 39083533, 2024). "Here, infection with O. ostertagi induced the expression of some Tuft cell markers, including POU2F3, CHAT, TRPM5, and GFI1B in cattle." (PMID 40076885, 2025). "The systemic immune response following infection with H. diminuta was similar in Pou2f3-/- and WT mice." (PMID 39083533, 2024). "The goblet cell response that follows infection with H. diminuta was delayed in Pou2f3-/- mice, possibly as a consequence of reduced or delayed IL-4/IL-13 signaling downstream of tuft cell activation." (PMID 39083533, 2024). "In order to quantify mucus metaplasia in whole lungs of control and Pou2f3-/- animals, we analyzed gene expression of goblet cell markers, Foxa3, Agr2, Muc5ac, and Muc5b, 51 days post infection." (PMID 36073526, 2022). "In the Pou2f3−/− mouse, expulsion of N. brasiliensis is delayed, indicating that in this model of infection with helminth parasites, ETCs coordinate timely worm expulsion via the initiation of a type 2 immune response." (PMID 34578195, 2021). "The percentage of POU2F3+ cells was greater in all three regions post-infection relative to helminth-naïve animals." (PMID 34880874, 2021). "We additionally infected Pou2f3+/-Stat1-/- and Pou2f3-/-Stat1-/- with MNoV strain WU23 containing L514, and found that while lethality was delayed in Pou2f3-/-Stat1-/- mice compared to Pou2f3+/-Stat1-/- littermates, all mice succumbed to infection." (PMID 33705489, 2021). "In contrast, mice deficient in tuft cells, through knockout of tuft cell specific transcription factor POU2F3, presented numerous worms 42 days post-infection." (PMID 31783921, 2019). "While Pou2f3-deficient mice lacking tuft cells showed an attenuated response to double RV infection, the limited response to a single infection on day 6 of life was generally maintained." (PMID 38061015, 2024). "Similarly, Pou2f3-/- mice harbour a small population of adult N. brasiliensis, for more than a month past the timepoint by which WT mice completely clear the infection." (PMID 39083533, 2024). "To address if a relatively minor population of Krt5+ cells may be converting to AT2s, we double stained for Krt5 and the AT2 cell marker SPC+ in Pou2f3-/- and control lungs at 25 days after infection to label cells in the process of conversion." (PMID 36073526, 2022). "Furthermore, we illustrate that IL-33 triggers the excessive generation of medullary thymic epithelial cell (mTEC) IV (thymic tuft cells) in a Pou2f3-dependent manner, as a consequence, disturbs mTEC/cortical TEC (cTEC) compartment and causes thymic involution during severe infection." (PMID 36371464, 2022). "Tuft cell deficient animals (Pou2f3−/−) show reduced total goblet cells and only a focal goblet cell hyperplasia, as well as reduced goblet cell expression of Retnlβ mRNA (codes for Resistin-like molecule (RELM) β) in response to infection with N. brasiliensis." (PMID 34578195, 2021). "ILC2 number was significantly reduced, though not abolished, in Pou2f3–/– mice following heterologous infection." (PMID 38061015, 2024). "Infection with H. diminuta resulted in a significant (p<0.05) increase in jejunal PAS+ goblet cells at 8, 11 and 14 dpi in WT mice, but a delayed increase in goblet cells at 11 dpi in Pou2f3-/- littermates." (PMID 39083533, 2024).
infection (continued). "Worm antigen and mitogen evoked production of IL-4 and IL-10 by splenocytes from wild-type and Pou2f3-/- mice was not appreciably different, suggesting similar systemic immune reactivity to infection with H. diminuta." (PMID 39083533, 2024). "Analysis of stool, ileum, colon, MLN, and spleen viral levels in survivors at 14 dpi demonstrated equivalent viral levels in Pou2f3+/-Stat1-/- and Pou2f3-/-Stat1-/-, supporting that CR6F514I infection of intestinal and extraintestinal tissues of Stat1-/- mice is tuft cell-independent." (PMID 33705489, 2021).
benign tumors (1 paper, 2024). "Because WTs and PAs are benign and consistently harbored FOX1- and POU2F3-positive cells, the frequencies of FOXI1 and POU2F3 expression were significantly higher in benign tumors than malignant ones, although our cases were not chronologically selected in this study." (PMID 38358561, 2024).
infectious disease (1 paper, 2025). A disorder directly resulting from the presence and activity of a microbial, viral, or parasitic agent in humans. "Pou2f3 has been identified as the crucial transcription factor for the differentiation and expansion of tuft cells in infectious diseases, and thus there was a strong possibility that TSG-6 could regulate the development of tuft cells by interacting with Pou2f3." (PMID 40301757, 2025).
POU2F3 also shares sentences with these, for which no sentence is quoted: coronary artery disease (4 papers); gastric cancer (3); neuroendocrine carcinoma (3); acute coronary syndrome (2); adenocarcinoma (2); atherosclerosis (2); bladder squamous cell carcinoma (2); carcinoids (2); cardiovascular disease (2); deep venous thrombosis (2); genetic diseases (2); hereditary spastic paraplegia (2); ischaemic stroke (2); malaria (2); myocardial infarction (2); Stroke (2); airway hyperresponsiveness (1); Allergy (1); Alzheimer disease (1); amyotrophic lateral sclerosis (1); Anosmia (1); bacterial infection (1); basaloid squamous cell carcinoma (1); bladder NECs (1); brain ischemia (1); cervical intraepithelial neoplasia (1); Cirrhosis (1); colorectal cancer (1); ductal carcinoma in situ (1); falciparum malaria (1).
A further 26 diseases each share a sentence with POU2F3 in 1 paper.